IL17A (interleukin 17A)
Diseases named in the same sentence as IL17A in open-access papers (continued):
Sharing a sentence is not in itself a finding about the gene and the disease.
Crohn disease (continued). "However, the failure of anti-IL17A antibody therapy for Crohn's disease in phase II clinical trials has questioned the postulated role of IL-17A in a pathogenetic mechanism of inflammatory GI diseases." (PMID 24796324, 2014). "Our findings may explain why anti–IL-17A treatment does not have benefits or even exacerbation of Crohn’s disease, which is caused by excessive proinflammation and immune cell infiltration." (PMID 40749055, 2025). "However, single IL-17A inhibition induced paradoxical effects in patients with Crohn’s disease and some cases of de novo glomerulonephritis, possibly due to the complete Th1 cell response, along with the concomitant downregulation of regulatory T cells (Tregs)." (PMID 38418932, 2024). "Moreover, longitudinal measurements of the proportion of ILCs based on the clinical course of the disease after initiating anti-IL-17A therapy may be helpful for understanding ILC differentiation in the context of blocking IL-17A in Crohn’s disease." (PMID 31941937, 2020). "However, Th17 cells’ complex polarity and epithelial barrier integrity may not be the only possible explanation for the failure of anti-IL-17A therapy in Crohn’s disease, because RORγt+ innate lymphoid cells (ILCs) also produce IL-17A18." (PMID 31941937, 2020). "However, a putative protective role of IL-17 in Crohn's disease may explain, at least in part, the worsening of gut inflammation in some cases upon inhibition of IL-17A." (PMID 31402919, 2019). "Elevated levels of IL-17A und IL-17F have been found in patients with IBD and the increased concentration of IL-17A within the lamina propria of patients with Crohn’s disease suggested a possible therapeutic target." (PMID 38060157, 2024). "By contrast, clinical trials of anti–IL-17A or anti–IL-17RA Abs show no clinical benefits or even exacerbation of Crohn’s disease." (PMID 40749055, 2025). "There is a unique population of TNFα + IL-17A + CD4 + T_RM cells in Crohn’s disease which are largely absent in controls." (PMID 38420127, 2024). "Although these findings make Th17 cells a reasonable target for controlling renal immune-mediated diseases, IL-17A blockade did not benefit some Crohn’s disease patients." (PMID 38418932, 2024). "We hypothesized that high-dose vitamin D treatment alone or in combination with infliximab in patients with active Crohn’s disease decreases the mucosal expression of IL22, IL17A and IL17F and increases the mucosal VDR expression." (PMID 33266022, 2020). "Th17 cells may also have protective functions; the neutralization of IL-17A failed to induce any improvement in Crohn’s disease." (PMID 37189778, 2023). "In humans, serum IL-17A may reflect the active phase in ulcerative colitis, but not in Crohn’s disease, but whether there is such a division of responses in IL-17A and 17F in the skin is still not established." (PMID 38567051, 2023). "It is suggested that acupuncture may not inhibit the expression of IL-17A and IL-22 in Crohn's disease model rats." (PMID 35075366, 2022). "Furthermore, MALT1 was positively related to C‐reactive protein (CRP), TNF‐α, IL‐17A, and mayo score in A‐UC patients; positively correlated with CRP, erythrocyte sedimentation rate, TNF‐α, and Crohn's disease activity index score in A‐CD patients." (PMID 34997981, 2022). "Laboratory research following the failed human trials of anti-IL-17A in Crohn’s disease led to observations that γδ T-cell IL-17A production in the gut is produced independent of IL-23R signalling where IL -17 signalling was required for maintaining intestinal occludin junctions." (PMID 33815371, 2021). "However in Crohns disease blockade of IL-23 was effective while blockade of IL-17A or IL-17RA was not." (PMID 34552583, 2021). "Our study suggests that interleukin 17A may diverse active phase from remission only in ulcerative colitis but not in Crohn’s disease." (PMID 32724117, 2020).
Crohn disease (continued). "However, anti-IL-17A therapy does not improve clinical outcomes in patients with Crohn’s disease." (PMID 31941937, 2020). "Complete blockage of IL-17A failed to ameliorate intestinal inflammation in Crohn's disease, which might be explained by preventing the beneficial actions of IL-17A, such as promotion of AMP production that ultimately protects the host against invading microbes." (PMID 30697217, 2018). "In fact, our findings were well correlated with the report about GSE111761 that in patients with Crohn’s disease receiving anti-TNF therapy, there were significant upregulations of mucosal Il-23p19, Il23R and Il17A in non-responders, but not in responders." (PMID 33193322, 2020). "Furthermore, the expression of IL17A mRNA and FOXP3 transcripts lacking exon 7 correlates in Crohn’s disease biopsies and peripheral blood from coronary artery disease patients, indicating that skipping of exon 7 is a common event for IL-17 expression in diverse settings." (PMID 29593749, 2018).
pulmonary fibrosis (213 papers, 2011 to 2026). Chronic progressive interstitial lung disorder characterized by the replacement of the lung tissue by connective tissue, leading to progressive dyspnea, respiratory failure, or right heart failure. "In conclusion, we found IL-22 mediated an anti-fibrogenesis effect in the bleomycin-induced pulmonary fibrosis model and the effect associated with inhibition of IL-17A." (PMID 36564791, 2022). "IL-22 mediated an anti-fibrogenesis effect in the bleomycin-induced pulmonary fibrosis model and this effect was associated with inhibition of IL-17A." (PMID 36564791, 2022). "IL-17A expression has been implicated in the pathogenesis of pulmonary fibrosis, chronic allograft rejection, fibrosis in orthotopic lung transplantation, myocardial fibrosis, and hepatitis-induced hepatic fibrosis." (PMID 33381124, 2020). "IL-17A produced by Th17 cells is associated with abnormal recruitment of neutrophils, resulting in persistent neutrophilia and an increase in lung fibrosis through the induction of vascular endothelial cell apoptosis." (PMID 31398940, 2019). "In particular, IL-1β-induced and bleomycin-induced lung fibrosis seems to depend on the action of IL-17A, and in addition, IL-17A−/− mice are less susceptible to experimental skin fibrosis." (PMID 23834907, 2013). "IL-17A, a cytokine produced predominantly by Th17 cells, has been implicated in promoting fibroblast activation, neutrophilic inflammation, and extracellular matrix remodeling in experimental models of pulmonary fibrosis." (PMID 40612945, 2025). "Furthermore, IL-17A has been implicated in promoting alveolar epithelial cell apoptosis and exacerbating the progression of pulmonary fibrosis, disrupting normal alveolar architecture and impairing alveolar–capillary gas exchange." (PMID 39066169, 2024). "Additionally, IL-17a has been implicated in pro-fibrotic responses and development of pulmonary fibrosis." (PMID 37744375, 2023). "Moreover, in murine models of bleomycin-induced lung injury, IL-17 receptor A- or IL-17A-deficient mice displayed substantially reduced pulmonary fibrosis in contrast to wild-type mice." (PMID 32849634, 2020). "Thus, IL-17A was shown to participate to bleomycin-induced lung and skin fibrosis, IL-17A deficiency attenuated skin thickness in tight skin-1 mice and neutralization of IL-17A inhibited silica-induced chronic inflammation and pulmonary fibrosis." (PMID 25136988, 2014). "Furthermore, animal studies illustrated that IL-17A deficiency could mitigate bleomycin and radiation-induced pulmonary fibrosis." (PMID 36544757, 2022). "Dysregulation of the gut microbiota can exacerbate pulmonary fibrosis by enhancing the IL-17A signaling pathway." (PMID 41383739, 2025). "Neutrophils and Th17 cells are critical in PD-induced aggravation of pulmonary fibrosis, and Th17 cells regulate neutrophils via IL-17A." (PMID 40496020, 2025). "Various studies have confirmed the importance of neutrophils, Th17 cells and IL-17A in pulmonary fibrosis." (PMID 40496020, 2025). "In our study, neutrophils and Th17 cells were demonstrated indispensable for PD-induced exacerbation of pulmonary fibrosis, and Th17 cells regulated neutrophils via IL-17A to aggravate pulmonary fibrosis." (PMID 40496020, 2025). "Aerobic exercise for 4 weeks ameliorated silica-induced lung fibrosis in mice through the inhibition of the IL-17A/CXCL5/Chemokine (C-X-C motif) Receptor 2 (CXCR2) axis." (PMID 39796197, 2025). "Human data suggest that IL-17A secreted by Th17 cells promotes fibroblast proliferation and myofibroblast transformation through IL-17RA-dependent signaling, thereby promoting lung fibrosis." (PMID 40433386, 2025). "To further investigate the importance of neutrophils and Th17 cells in PD-induced aggravation of pulmonary fibrosis, we depleted neutrophils or IL-17A (mainly generated by Th17 cells) to assess the severity of lung fibrosis in mice." (PMID 40496020, 2025).
pulmonary fibrosis (continued). "IL-17A-neutralizing antibodies or IL-17A inhibitors significantly attenuated pulmonary fibrosis in silicosis mice and radiation-induced lung injury and fibrosis in mice." (PMID 40433386, 2025). "In experimental studies on a model of bleomycin-induced pulmonary fibrosis, it was shown that IL-17A is secreted by Th17 and acts as one of the inducers and factors of progression of fibrous remodeling of the pulmonary parenchyma." (PMID 39201632, 2024). "An important contribution of certain cytokines, such as IL-17A, IL-6, and IL-8 in pulmonary fibrosis has been observed." (PMID 38263193, 2024). "In this study, our findings established the biological significance of parasympathetic activation, α7nAchR, Th17 cells, and IL17A as potential therapeutic targets for patients suffering from lung fibrosis-induced PH." (PMID 37064881, 2023). "We also reported higher IL-17A concentrations in SSc, incremented cytokines in pulmonary fibrosis, and esophagus involvement." (PMID 37445745, 2023). "In BLM-induced pulmonary fibrosis, daphnetin significantly inhibited the production of IL-17A protein and mRNA induced by BLM in lung tissue." (PMID 38132116, 2023). "Lung fibrosis can now be mediated by IL-17A, which likely explains the increased symptoms after menopause." (PMID 36899902, 2023). "In idiopathic pulmonary fibrosis, IL-17A signaling is upregulated and demonstrated to be pathologic in multiple models of lung fibrosis." (PMID 37159282, 2023). "Accordingly, the neutralization of IL-17A induces the accumulation of Tregs and alleviates silica-induced pulmonary fibrosis in murine models." (PMID 36788232, 2023). "Currently, Studies have revealed that IL-17A, IL-17B, and IL-17E are all involved in the development and promotion of pulmonary fibrosis." (PMID 37858084, 2023). "CD4+lymphocytes increased in lung biopsy samples of RA-UIP patients, as well as Th17 cells participated in pulmonary fibrosis by release of IL-17A and TGF-β promoting the proliferation of fibroblasts and the formation of extracellular matrix." (PMID 37563706, 2023). "Numerous studies have indicated that IL17A promotes the release of inflammatory factors and contributes to the development of pulmonary fibrosis 59,60." (PMID 37781522, 2023). "Since it is known that IL-17A regulates matrix metalloproteinases (MMPs) and that MMPs contribute to the pathogenesis of pulmonary fibrosis, we determined the levels of MMPs in the lungs of M. intracellulare-infected mice." (PMID 35363832, 2022). "Our study also confirmed that giving the IL-17A neutralizing antibody decreased pulmonary fibrosis and collagen deposition in both WT mice and IL-22KO mice." (PMID 36564791, 2022). "Treatment with an anti-interleukin-23 antibody attenuated airway inflammation as well as fibrosis and reduced interleukin-17A and -22 levels in a murine model with the exacerbation of pulmonary fibrosis." (PMID 35163689, 2022). "Of these, IL-17A has been shown to play an important role in pulmonary fibrosis by promoting collagen production." (PMID 35360873, 2022). "Recently, a strong pro‐inflammatory cytokine IL‐17A has been proven to promote lung fibrosis, while the mechanism is unclear." (PMID 36308405, 2022). "IL-17A induces the aggregation of inflammatory cells and the release of inflammatory factors, which promotes the development of pulmonary fibrosis, while IL-22 protects epithelial cells and plays an anti-fibrotic role." (PMID 36564791, 2022). "Overexpression or abnormal activity of IL-17A under pathological conditions can drive pulmonary fibrosis." (PMID 35550651, 2022). "Other findings report that TGF-β regulates the differentiation of Th17 cells, which specifically affect the secretion of IL-17A at the early stage of inflammation and pulmonary fibrosis." (PMID 35739565, 2022).
pulmonary fibrosis (continued). "Mechanistically, IL-22 reduced the Th17 cell proportion and IL-17A mRNA level in lung tissues, and treatment with an IL-17A neutralizing antibody alleviated the severe pulmonary fibrosis in IL-22 knockout mice." (PMID 36564791, 2022). "IL-17A is involved in respiratory diseases such as bronchial asthma and can promote collagen formation and pulmonary fibrosis." (PMID 36564791, 2022). "The distinctions in the percentages of CD4 + IL-6+ and CD4 + IL-17A + T cells among mice in different housing cohorts support microbiota-induced alterations to the IL-6/ STAT3/IL-17A pathway in pulmonary fibrosis." (PMID 36543914, 2022). "It has been suggested that blocking IL-17A can also inhibit Calcium cascade which help to attenuate lung fibrosis." (PMID 35603223, 2022). "We investigated the role of IL-22 on bleomycin-induced pulmonary fibrosis and the mechanism in the possible interaction between IL-22 and IL-17A." (PMID 36564791, 2022). "Except for TGF-β other cytokines involved in Th17 differentiation are indicated to induce lung fibrosis as well, suggesting potential role of IL-17A in pulmonary remodeling." (PMID 35603223, 2022). "Taken together, these findings reveal that the gradually rising of IL-17A occurs concomitantly with an increasing cumulative burden of PM exposure, implying that IL-17A plays an important role in the onset of pulmonary fibrosis." (PMID 35739565, 2022). "It has been recently proposed that IL-17A induces protein and mRNA regulation of C3, and limiting complement activation by neutralising IL-17A is a potential mechanism for ameliorating pulmonary fibrosis." (PMID 36605203, 2022). "Here, we show that the interplay between IL-17A and MDSCs plays an important role in promoting PM-induced pulmonary fibrosis." (PMID 35739565, 2022). "Overall, our study implicates the low-diversity gut microbiota as a contributor of pulmonary fibrosis severity through their capacity to activate the IL-6/STAT3/IL-17A signaling pathway." (PMID 36543914, 2022). "In this study, we investigated the role of IL-22 on bleomycin-induced pulmonary fibrosis and the possible interaction between IL-22 and IL-17A." (PMID 36564791, 2022). "It was also suggested that IL-17A contributes to the transformation of myofibroblasts and promotes skin and lung fibrosis." (PMID 35686127, 2022). "CD103high Tregs can constrain lung fibrosis induced by CD103low tissue-resident pathogenic CD4+ T cells with higher production of effector cytokines, such as IL-4, IL-5, IL-13, IL-17A, and IFN-γ." (PMID 34488453, 2021). "The observation that IL-17A is upregulated is consistent with previous reports showing that IL-17A is a contributing factor to the molecular pathways that regulate pulmonary fibrosis." (PMID 32899668, 2020). "In murine bleomycin-induced pulmonary fibrosis, IL-17A+/γδ+ T cells prevented pulmonary fibrosis, apparently through attenuation of interstitial inflammation and improving epithelial regeneration." (PMID 32987705, 2020). "Conversely, inflammatory models with suppression of IL-17 revealed the amelioration of fibrosis, while pulmonary fibrosis models showed that cardiac fibroblasts were encouraged by IL-17A to proliferate and migrate." (PMID 30915354, 2019). "This study successfully established HSV1 infection‐induced AE‐IPF in mice with BLM‐induced lung fibrosis and found that IL‐17A and ERS played key roles in the acute lung injury in AE‐IPF." (PMID 30378252, 2019). "Treatment with IL-1RA suppresses IL-23 and IL-17A production and attenuates the symptoms of idiopathic pulmonary fibrosis." (PMID 29254155, 2017). "Our previous work indicates that Th17 cells and cytokine IL-17A participate in the development of pulmonary fibrosis through suppressing autophagy." (PMID 28039485, 2017).